CCND1 (cyclin D1)
Diseases named in the same sentence as CCND1 in open-access papers (continued):
Sharing a sentence is not in itself a finding about the gene and the disease.
colorectal cancer (continued). "Conspicuously, we notice that 5 genes (CDK6, E2F3, CCND1, SMAD4 and CDKN1B) are associated with cell cycle, colorectal cancer, pancreatic cancer, chronic myeloid leukemia, and small cell lung cancer in the cluster of Group A." (PMID 26221171, 2015). "There is some debate as to the utility of Ki-67, PCNA, CCND1, and nm23 expressions as prognostic factors in colorectal cancer." (PMID 26689966, 2015). "Abnormal activation of two-crucial pathways results in overexpression of downstream target proteins c-Myc and cyclin D1 and thus induces the proliferation of colorectal cancer cells." (PMID 25386960, 2014). "Taken together, our results suggest that BITC inhibits β-catenin-dependent cyclin D1 transcription and cell proliferation through the nuclear translocation of p65 in human colorectal cancer cells." (PMID 25412312, 2014). "Eleven studies reported data on the correlation between cyclin D1 expression and colorectal cancer patients' age." (PMID 24728073, 2014). "Of the 22 studies, 21 studies reported the prognostic value of cyclin D1 expression for OS in patients with colorectal cancer." (PMID 24728073, 2014). "The differential expression of the genes AXIN2 and CCND1 in the three colorectal cancer cell lines highlights the fact that the genetic background of a given cell has a major impact on the expression of a specific gene." (PMID 24467841, 2014). "Despite a well-established role of cyclin D1 in cell cycle progression, previous data on cyclin D1 and clinical outcome in colorectal cancer have been conflicting." (PMID 24728073, 2014). "Results of overall and subgroup analyses for effects of cyclin D1 expression on overall and disease-free survival in colorectal cancer." (PMID 24728073, 2014). "Cyclin D1 plays a vital role in cancer cell cycle progression and is overexpressed in many human cancers, including colorectal cancer (CRC)." (PMID 24728073, 2014). "Cyclin D1 expression is known to be upregulated in a variety of tumor types and occurs in one-third or more of colorectal cancers." (PMID 24728073, 2014). "Previous studies reported that there existed differences in nuclear cyclin D1 overexpression for colorectal cancer (11–30%)." (PMID 24728073, 2014). "NF-kappaB was also considered as one of the major contributors in the oncogenesis of chronic inflammation-induced colorectal carcinomas, most likely through the upregulation of its pro-survival target genes including cyclin D1, VEGF, IL-8, COX2, and MMP9." (PMID 24571667, 2014). "Cyclin D1 is known to be a predictive factor for therapeutic response of colorectal carcinoma whereas cyclin D2 is required for the CDK4/6-driven growth of colorectal adenoma cells." (PMID 24765199, 2014). "In several studies over-expression (Cyclin D1, NF-κB, PCNA, MMP-2) or loss of expression (Bcl-2, APC) of these molecules have been found to be associated with more aggressive tumor growth in colorectal cancer." (PMID 23326301, 2013). "Beta-catenin, as a transcription factor complexed with TCF4, is known to upregulate expression of many relevant proteins in colorectal cancer, such as c-myc, cyclin D1, LEF-1, CD44, and c-jun." (PMID 22682314, 2012). "We also reported that MSP58 regulates colorectal cancer cell proliferation, development, and apoptosis, by the cyclin D1-cyclin-dependent kinase 4-p21 pathway." (PMID 22773039, 2012). "We had reported that MSP58 regulates colorectal cancer cell proliferation, development, and apoptosis, by the cyclin D1-cyclin-dependent kinase 4-p21 pathway." (PMID 22773039, 2012). "We also found that MSP58 regulates colorectal cancer cell proliferation, development, and apoptosis, by the cyclin D1-cyclin-dependent kinase 4-p21 pathway." (PMID 22773039, 2012). "The SAM programme typed mRNA of transcripts of the VEGFA, VEGFC, and CCND1 encoding genes to be statistically significant in the compared groups as genes differentiating stages III and IV of clinical progression of colorectal cancer." (PMID 22363883, 2011).
colorectal cancer (continued). "Overexpression of cyclin D1 induces excessive cellular proliferation and is a feature of a number of cancers, including endometrial and colorectal cancer." (PMID 18822177, 2008). "Moreover, we assessed whether CCND1 genotype modified the effect of a sporadic (nonsyndromic) family history of colorectal cancer as well as the effect of other dietary and lifestyle risk factors for colorectal cancer and adenoma." (PMID 16495921, 2006). "Multivariate analysis shows that cyclin D1 and A are two independent prognostic factors in colorectal cancer patients." (PMID 15385053, 2004). "The expression of cyclin D1, cyclin A, histone H3 and Ki-67 was examined in 60 colorectal cancer cases for co-regulation and impact on overall survival using immunohistochemistry, southern blot and in situ hybridization techniques." (PMID 15385053, 2004). "Elevated β-catenin levels in human colorectal cancer (CRC) cells lead to increased trans-activation of ‘protumorigenic’ β-catenin/T-cell factor (TCF) target genes such as cyclin D1." (PMID 15188006, 2004). "Previous studies have demonstrated that cyclin D1 is increased in adenomatous polyps and in both sporadic and familial forms of colorectal cancer." (PMID 12189559, 2002). "DIM modulates cyclin D1 expression by activating ER stress in colorectal cancer cells." (PMID 40822462, 2025). "Similarly, miR‐6125 has been shown to downregulate YTHDF2 and inhibit the growth of colorectal cancer cells by downregulating cyclin D1." (PMID 40231553, 2025). "Moreover, its treatment reduced colorectal cancer proliferation by modulating the NF‐κB pathway and Bax expression while suppressing Bcl‐2, cyclin‐D1, c‐myc, and NLRP3 expression." (PMID 40321606, 2025). "Aspirin induced human colorectal cancer (CRC) cell apoptosis by suppressing Cyclin D1/CDK4 pathway." (PMID 39161904, 2024). "Indeed, several of the compounds reduced EpCAM-mediated cyclin D1 (CCND1) expression in colorectal carcinoma cell line HCT-8; however, they have yet to be tested against tumor growth." (PMID 38612911, 2024). "In addition, the diterpenoid compounds, found in the lipidic fraction of green coffee beans, such as kahweol, for instance, have been reported to reduce cyclin D1 degradation, thus inhibiting the proliferation of human colorectal cancer cells." (PMID 37176897, 2023). "However, the prognostic and therapeutic contributions of cyclin D1 to colorectal cancer (CRC) remain controversial." (PMID 36675501, 2023). "Additionally, transcriptional activation of p21 contributes to the inhibition of colorectal cancer cell growth and the degradation of cyclin D1, which participates in cell cycle progression and can function as a transcriptional co-regulator." (PMID 37242455, 2023). "In the AOM/DSS-induced mouse colorectal cancer model, cyclin D1 was decreased in the tumors from MG53-TG mice, but increased in those from the MG53-KO mice, relative to their corresponding wild type littermates, reinforcing the role of MG53 in facilitating cyclin D1 degradation." (PMID 37414783, 2023). "Recent studies have shown that inhibition of the activation of STAT3 could sensitize the effect of 5-FU by down-regulating cyclin D1 in colorectal cancer cells." (PMID 36157053, 2022). "On the other hand, a series of studies report the effect of some natural compounds on the expression of cyclin D1 in models of colorectal cancer, such as diospyros kaki thunb (DKC), which decreased protein and mRNA levels at concentrations of 50 μg/mL, mainly in SW480 cells, after 24 h." (PMID 36432565, 2022). "Furthermore, cyclin D1 is also directly targeted by miR-593-5p in colorectal cancer cells and by miR-1296 in breast cancer cells." (PMID 35444536, 2022). "To confirm whether PGC-1α regulates the expression levels of LARS1, p-AKT, p-GSK-3β, p-mTOR, p-S6K1, p-4EBP1, β-catenin, c-Myc, cyclin D1, and vimentin in other colorectal cancer HT-29 and SNU-C4 cells, we performed qRT-PCR and Western blot analysis." (PMID 36612155, 2022).
colorectal cancer (continued). "Moreover, nootkatone treatment inhibited cell proliferation in colorectal cancer cells, as evidenced by a reduction in cyclin D1." (PMID 35631492, 2022). "Studies have also shown that high expression of eIF4E in invalids with colorectal cancer predict high risk of hepatic metastases and their related mechanism may be partly by the regulation of the levels of VEGF, cyclin D1, MMP-2, and MMP-9." (PMID 36118897, 2022). "In addition, hsa-mir-30d overexpression inhibits the activation of cyclin D1, cMyc, and catenin, three essential components of the Wnt/beta-catenin signaling pathway, thereby inhibiting the development of colorectal cancer." (PMID 36290366, 2022). "Indeed, earlier reports have suggested that Cyclin D1 acts downstream of CPE in colorectal cancer and osteosarcoma cells, to promote the proliferation of these cells." (PMID 35328535, 2022). "Likewise, the expression of IRS-4 was also related to the activation of Cyclin D1 and Rb1 in colorectal cancer, two markers also altered in our study." (PMID 35743985, 2022). "Finally, further analysis of immunohistochemical experiments found that the level of M2 macrophage infiltration in colorectal cancer tissues with high expression of CCND1 or VEGFA was also significantly increased." (PMID 34922547, 2021). "Overexpressed CDCA2 promotes proliferation of colorectal cancer (CRC) cells by targeting upregulation of cyclin D1 (CCND1) through activation of the phosphoinositide 3-kinase (PI3K)/AKT pathway, while a specific PI3K inhibitor (LY294002) blocks the pro-proliferative effect of CDCA2 on CRC cells." (PMID 34660326, 2021). "Interestingly, cleaved PARP was augmented by the downregulation of RBM22 and U2AF1, suggesting that RBM22 and U2AF1 inhibited apoptosis and promoted the tumor progression in colorectal cancer cells through cyclin B1 and/or cyclin D1-dissociated mechanisms." (PMID 34202873, 2021). "By contrast, the mechanism underlying the regulatory effects of CDC42EP3 on colorectal cancer were demonstrated through the detection of cancer-related signaling including Akt, CDK6, Cyclin D1 and PIK3CA, a reflection of the downregulation of Akt, p-Akt, CDK6, Cyclin D1 and PIK3CA." (PMID 33726765, 2021). "In addition, when the roles of the cyclin D1 protein were analyzed using the cancer pathway (colorectal cancer) provided by the KEGG database, there was substantial evidence to show that downregulation of this protein can reduce the cancer burden." (PMID 34836311, 2021). "Interestingly, Western blotting revealed a decrease in cyclin D1 in colorectal cancer cells (HCT116 cells) and pancreatic cancer cells (SUIT2 cells) but not esophageal cancer cells (OE33 cells) by the downregulation of SF3A1." (PMID 34202873, 2021). "Cell division cycle-associated protein 2 may target CCND1 by promoting PI3K/Akt pathway, thus promoting the abnormal proliferation of colorectal cancer cells." (PMID 33688358, 2021). "A recent study found that overexpression of CDCA2 may target CCND1 to promote colorectal cancer cell proliferation and tumorigenesis via activation of the PI3K/AKT pathway." (PMID 32716971, 2020). "Moreover, reduction of PIK3R1 induced apoptosis and cycle arrest in colorectal cancer cells by repressed cyclin D1 expression." (PMID 32817745, 2020). "This might suggest that the same case happened in colorectal cancer cells where CCND1 is regulated by NFE2L3 in colorectal tissue samples." (PMID 31191746, 2019). "Obatoclax triggered the proteasomal degradation of cyclin D1 by causing T286 phosphorylation of cyclin D1 in some but not all colorectal cancer cell lines." (PMID 30875757, 2019). "The colorectal cancer study data indicate that Obatoclax mediates decreased expression of cyclin D1 via accelerating proteasome-mediated cyclin D1 degradation; the inhibition of proteasomal degradation using MG132 abrogated the ability of Obatoclax to cause decreased cyclin D1 expression." (PMID 30875757, 2019).
colorectal cancer (continued). "Activation of cyclin D1 enhanced proliferation of human colorectal cancer cells." (PMID 30974047, 2019). "While our finding that Obatoclax can inhibit cyclin D1 in MI-BC cells was initially unexpected and has not previously been reported, a subsequent review of the literature revealed that two other studies have shown that Obatoclax can inhibit cyclin D1 in colorectal cancer cells." (PMID 30875757, 2019). "In spite of the likely functional related to the CCND1 A870G single nucleotide polymorphism, there is no consistency in published results concerning its association with colorectal cancer." (PMID 29511472, 2017). "It is known that tumorigenesis of colorectal cancer is multi stepped, and cyclin D1 protein may be involved in one of these multiple pathways." (PMID 29511472, 2017). "In addition, cyclin D1 overexpression has been reported to be significantly correlated with various cancers including human colorectal cancer." (PMID 28870200, 2017). "Although some investigations were conducted to distinguish the possible role of the SNP in colorectal cancer susceptibility, thus far no study has been performed on CCND1 to examine its impact on colorectal cancer risk in Iranian population." (PMID 29511472, 2017). "In the present study, we did not observe any association between the risk of colorectal cancer and CCND1 A870G polymorphism." (PMID 29511472, 2017). "Wnt signaling pathway has been reported to target cyclin D1 in human colorectal cancer cells." (PMID 28870200, 2017). "Thus, we investigated the regulatory effect of DKC-E70 on cyclin D1 expression in human colorectal cancer cells." (PMID 28870200, 2017). "In the current study, the GA or AA CCND1 genotypes were not even associated with a borderline increase in the risk of colorectal cancer among patients." (PMID 29511472, 2017). "Actually, the overexpression of cyclin D1 was observed in many human cancers such as endometrial, thyroid, urothelial bladder, breast, brain gliomas, esophageal and colorectal cancers." (PMID 28870200, 2017). "In addition, it induced cell growth arrest and apoptosis by activating ATF3 expression and cyclin D1 proteasomal degradation in colorectal cancer cells, SW480." (PMID 24962785, 2014). "Inhibiting the β-catenin/cyclin D1 pathway can prevent the onset of colorectal cancer." (PMID 25412312, 2014). "However, the prognostic value of cyclin D1 overexpression in colorectal cancer is conflicting and heterogeneous." (PMID 24728073, 2014). "Thus, up-regulation of ATF3 and down-regulation of cyclin D1 are major molecular targets for treatment of colorectal cancer." (PMID 24962785, 2014). "Cyclin D1 overexpression was observed in 68.3% of human colorectal cancer." (PMID 24962785, 2014). "Cyclin D1 overexpression was related markedly with poor OS in colorectal cancer patients treated by single surgery (HR: 0.77, 95% CI: 0.63–0.93, P = 0.006) and surgery as well as chemoradiation (HR: 0.63, 95% CI: 0.48–0.83, P = 0.001), without significant heterogeneity between studies." (PMID 24728073, 2014). "A recent study has shown that strong nuclear EGFR expression in colorectal carcinomas is associated with cyclin-D1 but not with gene EGFR amplification." (PMID 23947899, 2013). "In addition, rosiglitazone treatment of colorectal cancer cells caused to G1 arrest because increased expression of KLF4 by rosiglitazone leads to increased expression of p21 and decreased expression of cyclin D1." (PMID 23024650, 2012). "Interestingly, a number of colorectal cancer studies have observed cytoplasmic cyclin D1 in tumour specimens and at least one of these studies has reported that increased cytoplasmic cyclin D1 correlated with low proliferation." (PMID 17375037, 2007).
colorectal cancer (continued). "We therefore examined whether CCND1 genotype modified the influence of a common family history of colorectal cancer (i.e., a history in one or more first-degree relatives) on cancer and adenoma risk." (PMID 16495921, 2006). "Furthermore, it has been demonstrated in a clinical analysis that nearly 50% of tissue samples examined from 70 colorectal cancer patients expressed increased levels of cyclin D1." (PMID 16552434, 2006). "We assessed whether the influence of CCND1 genotype varied for proximal as compared to distal colorectal cancers." (PMID 16495921, 2006). "The CCND1 A870G genotype was associated with a modest, although nonsignificantly elevated risk of colorectal cancer (OR, 1.59; 95% CI, 0.98–2.57) in women." (PMID 16495921, 2006). "This accumulation of cyclin D1 in the cell may promote cell proliferation and the subsequent development of colorectal cancer." (PMID 16495921, 2006). "Similarly, Curcumin treatment of a colorectal cancer cell line has been demonstrated to regulate the NFκβ pathway, suppressing the expression of key regulatory genes involved in cell survival and cell cycles, such as cyclin D1, Bcl-2, VEGF, and MMP9." (PMID 36835252, 2023). "Therefore, understanding the regulatory mechanisms of CCND1 may help to develop strategies to combat colorectal cancer cell migration and invasion." (PMID 35795002, 2022). "It was demonstrated that miR-185 could suppress Wnt/β-catenin signalling and modulate the transcription and translation levels of downstream molecules of this pathway, including MYC and CCND1, in human colorectal cancer, thus exerting tumour suppressor effects." (PMID 32366240, 2020). "Indeed, cyclin D1 overexpression occurs in one-third or more of human colorectal cancers." (PMID 29554905, 2018). "Kahweol-mediated cyclin D1 degradation may contribute to the inhibition of human colorectal cancer cell proliferation, and kahweol was observed to significantly decrease TGF-β (transforming growth factor beta) stimulated expressions of type I collagen and CTGF in vitro." (PMID 30613574, 2018). "Importantly, cyclin D1 overexpression leads to uncontrolled cell proliferation and is linked to the development, progression, poor prognosis, and chemoresistance of a broad range of human malignancies, including colorectal cancer, thus making cyclin D1 a potential therapeutic target." (PMID 28035994, 2016). "Since the cyclin D1 is one of the major downstream targets of Wnt/β-catenin signaling and the DACH1 is associated with Wnt pathways in colorectal cancer, we hypothesized that DACH1 could also repress cyclin D1 abundance via inactivation of Wnt signaling in HCC." (PMID 25940701, 2015). "Nonetheless, no study, to date, has examined whether CCND1 genotype modifies the influence of PMH use on colorectal cancer and adenoma risk." (PMID 16495921, 2006). "Given the established role of cyclin-dependent kinases (CDKs) and cyclins in cell cycle regulation, we examined the expression of cyclin D1, cyclin E1, and CDK6 in colorectal cancer cells treated with CS&Z extract." (PMID 40429805, 2025). "PCA exhibits an anti-proliferative effect against colorectal cancer cells by repressing the protein expression of β-catenin, HDAC2, and cyclin D1." (PMID 40076435, 2025). "miR‐424‐5p was shown to promote proliferation and metastasis of colorectal cancer cells by targeting SCN4B and also to inhibit cell proliferation by targeting E2F7, Cyclin E1, Cyclin A2, and Cyclin D1." (PMID 40405535, 2025).